MMP2 (matrix metallopeptidase 2)
Diseases named in the same sentence as MMP2 in open-access papers (continued):
Sharing a sentence is not in itself a finding about the gene and the disease.
cancer (continued). "Matrix metalloproteinase-2 (MMP-2) has also been reported to be an important biomarker for the early diagnosis of cancer, and the MMP-2-cleavable peptide EGPLGVRGK can be used as a switch for nanoprobes for precision therapy." (PMID 38399272, 2024). "Matrix metalloproteinase (MMP)-2 is considered to contribute to cancer progression and metastasis by degrading type IV collagen, the most abundant component of the basement membrane." (PMID 38501028, 2024). "The expression of PTK2, USP19, LAMC2, VEGFA, EPHA2, and MMP2 varies greatly among different cancer samples and has relatively high expression." (PMID 38694917, 2024). "Silencing RFX1 attenuated hypoglycemic agent‐induced inhibition of cancer cell behaviours and MMP2 activity." (PMID 39636301, 2024). "The analysis of MMP2 expression between cancer tissues and adjacent normal tissues reveals a significant difference (P<0.001)." (PMID 38978899, 2024). "Since AP-1 is a key transcription factor that promotes MMP-2 transcription, decreasing the expression of MMP-2 facilitates the prevention of cancer progression and metastasis." (PMID 39301125, 2024). "Mounting research has demonstrated a strong link between the STAT3 signalling cascade and the regulation of matrix metalloproteinase expression and activation, notably MMP‐2, in cancer cells." (PMID 39121240, 2024). "MMP2 is investigated as a BC biomarker indicating cancer prognosis as its expression correlates with lymph node metastasis." (PMID 38212739, 2024). "An increase in the TIPM3 and RECK protein levels (3.21- and 1.35-fold increase respectively) and a decrease in the MMP2 protein level (0.46-fold) indicated that overexpression of CLEC19A reduced the ability of U87 cancer cell migration." (PMID 38167030, 2024). "The pH-responsive molecule 3-diethylaminopropyl isothiocyanate (DEAP) and HA-grafted Dox were conjugated to a peptide (GRVGLPG) cleavable by MMP-2, which was overexpressed in cancer cells." (PMID 38255307, 2024). "This indicates that nobiletin has the ability to hinder or prevent the development of cancer through the FAK/Akt/NFκB/MMP-2/9 pathway." (PMID 39834817, 2024). "We also investigated the impact of the microvesicles on cancer cell adherence and the expression of MMP2, a gene involved in cancer development, invasion, and metastasis." (PMID 38326490, 2024). "It has been reported that MMP2 is also upregulated in various solid and hematologic malignancies, thereby promoting cancer development." (PMID 38326490, 2024). "Like RPMI-8226 cells, the presence of adipocytes from normal, overweight, or obese individuals alone increased the activity of MMP-2 in cancer cells (p < 0.0001)." (PMID 37686623, 2023). "MMP-2 overexpression was shown in several cancer cell lines (C26, 4T1, and B16F10) as compared to the normal NIH-3T3 fibroblast cells by gelatin zymography and qRT-PCR." (PMID 36910721, 2023). "Matrix metalloproteinase‐2 (MMP‐2), a type IV collagenase and zinc‐dependent endopeptidase, is well‐known for degrading the extracellular matrix and promoting cancer metastasis." (PMID 38064181, 2023). "Patients with MM have heightened MMP-2, a factor that contributes to cancer invasion and angiogenesis." (PMID 37686623, 2023). "Only a few studies on the role of MMP-2 in cancer progression and metastasis in canine OS were performed." (PMID 37373007, 2023). "Many different MMPs act as modulators of the TME by degrading proteins in the ECM, but MMP-2, -9, and -14 are particularly involved in cancer cell invasion of many tumors." (PMID 37509428, 2023). "The intracranial tumors of injected MMP2-knockdown cells showed much smaller in size, indicating a pivotal role of MMP2 in cancer." (PMID 36677584, 2023). "MT1-MMP and MMP-2 are involved in the breakdown of proteins normally surrounding the cell; however, within cancer cells, these proteinases promote their growth and invasion." (PMID 37298452, 2023).
cancer (continued). "Numerous clinical and experimental studies have associated an increase in various MMPs particularly MMP-2 and MMP-9 with cancer development." (PMID 36938194, 2023). "In order to assess the impact of MMP‐2 KO on cancer cell migration, transwell migration assays were conducted on U2OS WT and KO cell lines." (PMID 38064181, 2023). "We tested protein expression for ZEB1 and the mesenchymal cancer cell proteins MMP2, SNAI2, and CD44 due to their upregulation in GBM vs. normal tissue." (PMID 37761927, 2023). "MMP-2, which functions to degrade cellular basement membranes, is necessary for malignant tumor cells to penetrate multiple basement membrane barriers around tissues, blood vessels, nerves, and muscles in the process of metastasis." (PMID 37180721, 2023). "The content of MT1-MMP and MMP-2 in normal cells is usually low but can reach higher levels in cancer cells." (PMID 37298452, 2023). "MMP‐2, while typically expressed in non‐cancerous cells, is found to be significantly overexpressed in many types of cancer." (PMID 38064181, 2023). "In Lewis cells, suppressing the activities of MMP-2/9 through the modulation of STAT3/MAPK/ERK/JNK signaling pathway significantly inhibited cancer metastasis." (PMID 37766868, 2023). "In recent years, numerous genetic studies on MMP-2 and MMP-9, along with their roles in cancer risk have been published." (PMID 37445754, 2023). "The most active compounds showed a good inhibitory effect toward MMP-2 and -9 and possessed potent anti-proliferative activity against different cancer cell lines, including MCF-7, PC-3, HL-60, K562, KG1, and A549." (PMID 37513440, 2023). "The upregulation not only of neurotrophins but also of factors such as matrix metalloproteinases (MMPs), particularly the gelatinases MMP-2 and -9, facilitates cancer cell migration through PNI at the stromal level." (PMID 36675378, 2023). "A recent meta-analysis evaluated the relationships of variants in MMP-2, MMP-7, and MMP-9 for cancer risk." (PMID 37138857, 2023). "These AGEs can also activate the RAGE/ERK/SP1/matrix metallopeptidase-2 (MMP2) cascade in cancer tissues." (PMID 36890832, 2023). "Our findings highlight the MMP‐2 gene as a promising additional target for combating cancer cell migration and metastasis." (PMID 38064181, 2023). "Ongoing studies on this group of enzymes suggest that cancer cells can secrete and/or induce osteoclasts to release enzymes, including MMP-2 and MMP-9, into the bone microenvironment." (PMID 38138968, 2023). "In this process, a large amount of accumulated lactate can activate TGFβ1/p38 MAPK/MMP2/9 signal axis and stimulate the mitochondrial activity of cancer cells to improve the invasion and metastasis ability of breast cancer cells." (PMID 37582735, 2023). "MMP2 expression is elevated in various human cancers, including colon, pancreatic, prostate, bladder, skin, breast, and ovarian carcinomas." (PMID 36700237, 2023). "Markers of invasion in cancer are multiple, but the matrix metallo-proteases (MMP2) are key in this process." (PMID 36835368, 2023). "It is possible that lEVs from cancer patients generate a pre-metastatic niche with a few Ca9-expressing cancer cells and stromal cells with a cancerous phenotype over expressing MMP2." (PMID 36975533, 2023). "MMP2 and MMP9 are a family of proteolytic enzymes implicated in the invasion and metastasis of numerous cancers because they degrade extracellular matrix components." (PMID 37239013, 2023). "Andrographolide is inactive for ERK and AKT signaling, down-regulates the PI3-K pathway, and inhibits MMP2 (matrix metalloproteinase 2) activity, which is a regulatory cancer pathway." (PMID 36677808, 2023). "Cells need the adhesive contacts and cellular networks for adhering to the basement membrane, but these networks can be cleaved by MMP‐2 so that cancer cell motility is promoted." (PMID 38012058, 2023).
cancer (continued). "Cancer aggressiveness-related proteins, such as N-cadherin, Vimentin, Twist, MMP-2, MMP-9, and MMP-13, and the glycolytic enzymes PKM2 and GLUT1 were upregulated in ERL-R cells." (PMID 36611972, 2023). "Studies have shown that CD9-positive exosomes generated from CAFs can be taken up by SGC cells, which promote cancer cell migration and invasion by activating the MMP2 signaling pathway." (PMID 36717783, 2023). "Relative cancer invasion markers matrix metalloproteinase 2 (MMP-2), E-cadherin, MMP-9, epithelial-cell adhesion molecule (EpCAM), and N-cadherin in the LOC model were detected via immunohistochemical (IHC) staining." (PMID 37771785, 2023). "IL-3 plays a vital role in the extravasation of cancer cells by promoting the production of matrix metallopeptidase 2 (MMP-2) by cancer cells, enhancing the invasiveness of cancer cells." (PMID 37056723, 2023). "Overexpression of MMP2 and MMP9 is associated with metastatic cell activity in many types of cancer." (PMID 37509417, 2023). "Increased levels of MMP2/9 are connected to invasion, migration, and metastasis, which are related to poor prognosis in patients with cancer." (PMID 36765716, 2023). "MMP-2, -3, -9 and -14 are overexpressed and associated with ECM remodeling in a variety of malignant tumors." (PMID 36906534, 2023). "Pro-MMP-2 released by stromal fibroblasts can be cleaved and activated by cancer-cell-derived MT1-MMP." (PMID 37046830, 2023). "TIMP-2 traditionally inhibits MMP-2 and -9, but, in aggressive cancers, TIMP-2 uniquely binds and activates pro-MMP-2 and MT1-MMP to stimulate MAPK/ERK signaling." (PMID 38288108, 2023). "In an ovarian metastasis model, ECM components such as fibronectin, vitronectin and collagen I were cleaved into small fragments by activated MMP-2 and facilitate cancer cell adhesion and invasion by binding to integrin receptors." (PMID 36639546, 2023). "For instance, in breast cancer, fisetin can reduce the expression of MMP-2/9 by upregulating Nrf2 expression and promoting HO-1 transcription, leading to a decrease in cancer cell motility and migration." (PMID 37626424, 2023). "Results indicated that cancer tissues had increased protein and activity levels of MMP2 compared to adjacent normal samples." (PMID 36677584, 2023). "The availability of VEGF can be upregulated by matrix metalloproteinase-2 (MMP2), a multifunctional protein in cancer." (PMID 37373394, 2023). "Membrane-type MMP-14, also known as MT1-MMP, is involved in the progression of various types of cancer and is an activator of MMP-2." (PMID 38003553, 2023). "The FAK/ILK/ERK/PI3K/NFB pathways are activated when FN1 binds to integrin, which causes overexpression of MMP-2 and MMP-9 and the destruction of the extracellular matrix (ECM) as well as the invasion of cancer cells." (PMID 37640804, 2023). "Uncarboxylated osteocalcin enhances the proliferation of MDA-MB-231 cells through the TGF-β1/SMAD3 signaling pathway and increases the metastatic potential of cancer cells via upregulation of MMP-2, MMP-13 and VEGF." (PMID 36765749, 2023). "It is important to remember that cancer cells express matrix metalloproteinases (MMPs), for example, MMP-2/-9, which degrade the ECM-generating pathways that allow migratory cells to invade freely." (PMID 37298837, 2023). "Metalloproteinases (MMPs), particularly MMP-2, are known to have crucial roles in cancer cell differentiation, invasion, and metastasis through their ability to degrade extracellular matrix proteins." (PMID 37507910, 2023). "This metabolic switch accompanies inhibition of EMT and metastatic characteristics of cancer cells; migration, invasion, and expression of matrix metalloproteinase-2 (MMP-2)." (PMID 36774778, 2023).
cancer (continued). "eHsp90 was first discovered to be secreted by cancer cells by Eustace and colleagues, who found that Hsp90 secreted by cancer cells activated MMP2 and increased invasion." (PMID 37958410, 2023). "The conducted research has shown that the activity of MMP-2 and -9 is higher in tissues affected by cancer compared to healthy tissues." (PMID 37895400, 2023). "MMP-2-mediated degradation of collagen I plays a critical role in the reduction of micromechanical properties in cancer tissues." (PMID 37901315, 2023). "Literature evidence suggests that the over-expression of MMP-2 is an active contributor to the progression of malignant GB and NB via increased cancer-cell growth, migration, invasion, and angiogenesis." (PMID 37444498, 2023). "MMP-2 and MMP-9 have also been implicated in cancer development and progression through their functions in cell apoptosis, proliferation, and angiogenesis." (PMID 36831550, 2023). "Another explanation is that MMP2-dependent cleavage of P2RX7 enables cancer cells to evade P2RX7-mediated cytotoxicity." (PMID 36803784, 2023). "Suppression of MMP-2 level significantly reduced, inhibited survival of cancer cells, and promoted radiosensitization." (PMID 37766868, 2023). "This impairment in cell migration in MMP‐2 KO cells provides further evidence of the MMP‐2 gene's involvement in cancer cell migratory pathways." (PMID 38064181, 2023). "Among the numerous MMPs identified (over 20 in total), MMP2 and MMP9 have been linked to the aggressive behavior of cancer." (PMID 38002335, 2023). "Scientists believe that targeting both the active site and the collagen-binding FN-II domains will show promising effects in inhibiting the MMP-2 role in cancer." (PMID 37513440, 2023). "There is a clear link between de novo lipogenesis in the liver and activation of the NF-κB pathway, which is involved in cancer metastasis via regulation of metalloproteinases MMP-2/9." (PMID 36982278, 2023). "Few articles investigated the predictive value of inflammatory biomarkers [interleukin (IL)-1β, IL-6, IL-10, TNF-α, and MMP-2 and -9] in the peritoneal fluid of cancer patients who underwent surgery and experienced AL in different locations." (PMID 37601530, 2023). "It has been observed that the actual activity of MMP- 9 is much higher than MMP-2 in all types of bladder tissues (nanokatals vs. picokatals/1 kg of total protein content) and is correlated with the grading of the cancer." (PMID 36979935, 2023). "Among these 70 coexpressed genes, we noticed two particular ones: MYC and MMP2, two well-recognized malignancy markers closely related to cancer cell proliferation, survival and invasion." (PMID 37667197, 2023). "And in this step, DDR1 was also revealed to play a role in the degradation of extracellular matrix through upregulation of MMP2 that facilitates cancer cell invasion." (PMID 37271822, 2023). "Some MMPs overexpression (such as MMP2, MMP9 and MMP13) were directly associated with poorer prognosis in many cancers." (PMID 36788565, 2023). "Although MMP‐2 is known to degrade the extracellular matrix and facilitate cancer cell invasion and metastasis, targeting extracellular MMPs clinically has proven insufficient in inhibiting metastasis." (PMID 38064181, 2023). "Cancer cells degrade the extracellular matrix barrier through secreting MMP2 and MMP9, and subsequently bind to adhesion receptors on the basement membrane, promoting cell mobility." (PMID 37940982, 2023). "Study showed that down-regulation of phosphorylation of JAK2/STAT3 significantly inhibited its downstream target genes MMP-2/9, thereby suppressing cancer metastasis and invasion in NSCLC." (PMID 37766868, 2023). "Cluster 2 (green) was associated with the upstream molecules of MMP and contained 6 terms, including metastasis, mmp, in-vitro, mmp-9, mmp-2, activation, nf-kappa-b, cancer-cells, iv collagenase, receptor." (PMID 36814819, 2023).
cancer (continued). "Overexpressed GSH in cancer can rapidly break the disulfide bond, and MMP-2 overexpressed in cancer can degrade the gelatin carrier, and through these two pathways, PTX can be released precisely and efficiently into the cancer lesion area." (PMID 37025360, 2023). "For instance, a novel nanovehicle model with potential of hydrogen (pH)/ROS/MMP-2 triple-responsive will gradually release anti-cancer drug when meets MMP-2-rich, low pH and high density of intracellular ROS." (PMID 36906534, 2023). "Since MMPs facilitate the degradation and modification of the ECM for metastasis, the activities of MMPs including MMP-2 and -9 are monitored to examine the potential anti-invasion effects of drugs on cancer cells." (PMID 37495969, 2023). "ZEB1 can promote drug resistance and the survival of cancer cells According to a study, after focal ischemia, gelatinase A (MMP-2) and gelatinase B (MMP-9) activities in the human brain increase." (PMID 36250005, 2022). "MMP-2/9 plays an important role in cancer invasion and metastasis, leading to transcription regulated by upstream regulatory factors NF-κ B, C-Jun and AP-1." (PMID 35335379, 2022). "Overall, these results indicate that deflamin exerts an inhibitory effect on the activity of both MMP-2 and -9, as well as on cancer cell migration and invasion, with important implications for cancer development and progression." (PMID 36551666, 2022). "This resulted in the upregulation of MDR1 gene, metalloproteinase inducer (CD147) and matrix metalloproteinases (MMP2 and MMP9), which are highly associated with the cancer cells invasiveness and migration, and MDR in cancer." (PMID 36233276, 2022). "During cancer development, Nav1.6 was significantly up-regulated with channels activities and then induced the secretion of matrix metalloproteinase type 2 (MMP-2), promoting cancer cells invasion and metastasis." (PMID 36033489, 2022). "Induction of LOX-PP expression by the adenoviral vector reduced cancer cell migration and hampered the expression of angiogenic factors MMP2 and MMP9." (PMID 35563478, 2022). "The EtOH extract, EtOAc soluble fraction, and GA extractives impaired the motility and invasion of cancer cells by prohibiting migration and proliferation by the downregulation of MMP2, MMP9, cleaved caspase-3, Bcl-2, and the upregulation of Bax." (PMID 36362345, 2022). "Oshima’s results show cancer cells expressing membrane-Type1-matrix metalloproteinase (MMP) are surrounded by macrophages, leading to the activation of MMP2, which increases the migration and invasion of cancer cells." (PMID 36249057, 2022). "Knowing their significant roles in cancer invasion and migration, the metalloproteinases MMP-2 and MMP-9 were also included in the analysis." (PMID 36613598, 2022). "The TMSB4X gene encodes for the thymosin beta 4 (Tβ4) protein, which is involved in hematopoietic stem cell function and mobilization, while the MMP-2 protein regulates cancer cell migration and invasion." (PMID 35955786, 2022). "Anti‐Chi3L1 antibody significantly decreased the expression of cancer growth and migration‐associated proteins, such as PCNA, cyclin D1, cyclin E, Cdk2, Cdk4, Cdk5, MMP2 and MMP9 in A549 lung metastasis model tissues." (PMID 34861103, 2022). "Exogenous CoQ10 reduces MMP-2 activity, along with the pro-oxidant capacity of cancer cells in a dose-proportionate manner." (PMID 36361913, 2022). "Here, overexpressed MMP2 participates in the process of the mesothelium-to-mesenchymal transition, favoring cancer dissemination." (PMID 35626752, 2022). "Various evidence indicate that MMP-2 along with MMP-9 are overexpressed in malignant tumors, including BC." (PMID 35295962, 2022). "Circ_MMP2 is plentiful in cancer cell-derived exosomes and can be transported into other cancer cells." (PMID 35055115, 2022). "It has been noticed that endothelial tight junctions are disrupted by cancer-secreted factors, such as MMP2, MMP9, and miR-105, inducing vascular permeability and metastasis." (PMID 35055115, 2022).